ARG1 (arginase 1)
Diseases named in the same sentence as ARG1 in open-access papers (continued):
Sharing a sentence is not in itself a finding about the gene and the disease.
ovarian carcinoma (25 papers, 2019 to 2025). A malignant neoplasm originating from the surface ovarian epithelium. "We identified that advanced stage or high stromal arginase-1 were associated with poor survival in ovarian cancer patients." (PMID 37996700, 2024). "The authors observed that overexpression of ARG1 in mouse ovarian cancer cells is associated with accelerated tumor progression and that the latter can be inhibited by an arginase inhibitor." (PMID 36498469, 2022). "Furthermore, increased ARG1 expression in mouse ovarian cancer cells was revealed to have an association with accelerated tumor progression that can be blocked through the use of an arginase inhibitor." (PMID 35563739, 2022). "Based on our gene expression analyses of the L-ARG/NO module and up-regulation of PRMT1/5/ARG1/2, we hypothesized that the pathogenesis and pathophysiology of ovarian cancer might be associated with systemic and circulating changes in SDMA and L-ARG metabolites." (PMID 37684587, 2023). "Ovarian cancer cells utilize extracellular vesicles to deliver arginase ARG1 to immune cells, which inhibits the proliferation of CD4+ and CD8+ T cells by affecting their arginine metabolism, thereby suppressing antitumor immune responses." (PMID 41184266, 2025). "We determined that TAMs had increased expression of IL-10, IL-6, CD206, and ARG1, whereas ovarian cancer cells had increased expression of IL-10, IL-6, VEGF, STAT3, and PD-L1." (PMID 36757936, 2023). "Ascites-derived and plasma-derived exosomes containing Arg-1 were found to suppress T-cell responses and promote tumor progression in ovarian carcinoma." (PMID 38001706, 2023). "Increased Arg-1 activity is seen in many tumours, such as head and neck cancer, and increased plasma levels have also been observed in ovarian cancer patients." (PMID 36835246, 2023). "PD-1 and CTLA-4 inhibitors can modulate the amount and activity of ARG-1, which prevents MDSCs from suppressing the immune system in ovarian cancer." (PMID 36311734, 2022). "In animal experiments, it was discovered that ovarian cancer cells express and release extracellular vesicles (EVs) containing ARG-1, which are taken up by DCs and prevent the proliferation of T cells." (PMID 36311734, 2022). "Ovarian cancer EVs have been shown to carry arginase 1 (ARG1), an enzyme that catalyzes the degradation of semi-essential L-arginine to L-ornithine and urea." (PMID 35563739, 2022). "An additional study on ovarian cancer patients revealed the presence of TEXs from ascites and plasma enriched in arginase‐1 (ARG‐1)." (PMID 33815694, 2021). "Previous studies have demonstrated that IDO1, ARG1 and iNOS are expressed in various types of cells in the ovarian cancer ascites." (PMID 32208517, 2020). "In preclinical models it has been shown to delay ovarian cancer progression and to revert ARG1-mediated inhibition of antigen-specific T-cells proliferation and to restore their CD3ζ levels." (PMID 32499785, 2020). "Taken together, these data indicate that ARG1 expressed by tumor cells accelerates tumor progression and is a potential therapeutic target in ovarian carcinoma." (PMID 31278254, 2019). "Here, the authors show that ovarian cancer cells produce small extracellular vescicles containing arginase 1 that are taken up by dendritic cells in the draining lymph nodes, resulting in inhibition of antigen-specific T-cell proliferation." (PMID 31278254, 2019). "Given that DDR2-regulated arginase activity in CAFs affected ovarian cancer tumor collagen production, we asked whether stromal arginase-1 expression correlated with ovarian cancer patient survival." (PMID 37996700, 2024). "Furthermore, high stromal arginase-1 expression correlated with poor survival in ovarian cancer patients." (PMID 37996700, 2024). "Notably, these differences are opposite to those expected in the case of elevated ARG1 and/or iNOS activity in ovarian cancer." (PMID 36765849, 2023).
ovarian carcinoma (continued). "In addition to IDO1 and IL4I1, enhanced ARG1 expression has previously been reported in the context of human ovarian cancer." (PMID 36765849, 2023). "F5-10 Cd38-/- EV are also enriched in Arginase-1, and therefore, may exert inhibitory functions on T cells, as it occurs with small EV found in the ascites and plasma of ovarian cancer patients." (PMID 36353645, 2022). "PRMT5, PRMT1, DDAH1, DDAH2, NOS2, ARG1, and ARG2 were all found to be up-regulated in the stage I/II or stage III/IV ovarian cancer tissues compared to normal tissues." (PMID 37684587, 2023). "The invasiveness of ovarian cancer cells is induced by various cytokines such as IL-10 and IL-6, which are secreted by the TAMs that have M2-like phenotypes and express CD206 and arginase-1 (ARG1)." (PMID 36757936, 2023). "It is reported ovarian cancer cells polarize macrophages toward an M2 phenotype in vivo which gradually gain expression of M2-like marker genes, such as CD206, Arg1, and CD163, at 4–8 weeks after tumor injection." (PMID 36035994, 2022). "In a mouse model of ovarian cancer with peritoneal metastasis, TIM4+ TAMs reduce mTORC1 activity through arginase-1-mediated arginine depletion, exhibiting higher mitochondrial OXPHOS and mitophagy activity, thus promoting ovarian cancer growth and peritoneal metastasis." (PMID 39430253, 2024). "Moreover, in this mouse ovarian tumor model, CAF-derived Arg1, as opposed to immune cell- or tumor cell-derived Arg1, was likely a significant contributor to overall arginase activity in ovarian cancer." (PMID 37996700, 2024). "The enzymatic activity of ARG1 in EVs from OvCa cell line supernatant or ascites of OvCa patients was higher than that of EVs isolated from benign cyst fluid, and research has demonstrated that ARG1+ EVs could inhibit CD4+ and CD8+ T cells in a dose-dependent manner in ovarian carcinoma." (PMID 34743730, 2021).
atherosclerosis (23 papers, 2012 to 2025). A disease characterized by the build-up of fatty material and calcium deposition in the arterial wall resulting in partial or complete occlusion of the arterial lumen. "Loss of the expression of arginase 1 (Arg1) and ornithine decarboxylase (Odc) in macrophages impairs atherosclerosis regression in mice, owing to defective MerTK expression and inefficient efferocytosis." (PMID 35499077, 2022). "In this context, the Arg-1 downstream metabolite putrescine regulates the ability of macrophages to uptake apoptotic cells, and disruptions in this pathway are linked with the propagation of tissue inflammation in atherosclerosis." (PMID 35430453, 2022). "In the context of atherosclerosis, a recent study has shown that upregulated expression of macrophage Arg-1 is crucial for resolving the accumulation of apoptotic cells by continual efferocytosis." (PMID 39198360, 2025). "The study demonstrated that Arg-1 and ornithine decarboxylase are critical in metabolizing apoptotic cell-derived arginine and ornithine to putrescine in efferocytosis in vivo and atherosclerosis regression." (PMID 39198360, 2025). "More recently, ARG1 was shown to aid the licensing of macrophages to clear multiple apoptotic cells, which would be expected to be important in atherosclerosis resolution." (PMID 33720008, 2021). "AsC treatment elevated Arg1 expression and reduced Cd86 expression in atherosclerosis, suggesting phenotypic switch to anti-inflammatory M2 macrophages." (PMID 31986489, 2020). "The M1 and M2 macrophages are characterized by abundant production of inducible nitric oxide synthase (iNOS) and arginase 1 (ARG1), respectively, which makes these relatively specific markers for macrophage polarization in atherosclerosis." (PMID 26226616, 2015). "Although Arg1 and CP are associated with several pathological processes, e.g., increased cardiovascular risk, immune-mediated reactions, and atherosclerosis, the results show that these enzymes do not seem to be associated with the severity of bruxism." (PMID 40990027, 2025). "ARG1 has been previously considered to be a beneficial factor in atherosclerosis." (PMID 33720008, 2021). "Arg1 is currently regarded as a new therapeutic target in atherosclerosis prevention." (PMID 24781446, 2014). "Following the progression of atherosclerosis over time, it was shown that plaque macrophages in early lesions express arginase-1 (indicative of AAMs), whereas at later time points the expression of arginase-2 (referred to as a CAM marker) predominated in the plaque." (PMID 22407286, 2012). "STAT6 signaling was shown to be necessary for the expression of many AAM markers, like arginase-1, but has not been directly linked to atherosclerosis development." (PMID 22407286, 2012). "Monocytes and monocyte-derived cells, expressing markers of “alternative activation” such as arginase-1 (Arg1) and mannose receptor (Mrc1, CD206), drive healing processes in animal models of cutaneous wounds, atherosclerosis, and myocardial ischemia." (PMID 37961609, 2023). "The level of the pro-inflammatory factor IL-1β was significantly decreased and the levels of anti-inflammatory factors eNOS, TGFβ, Arg1, and IL-10 were significantly increased after GLSP treatment in early and advanced atherosclerosis." (PMID 36923537, 2023). "M2 macrophages are anti-inflammatory macrophages identified by the expression of molecules such as IL-10, arginase 1 (Arg1), and Mrc1 (also known as CD206) and are involved in tissue repair, enhancing plaque stability during atherosclerosis 114-117." (PMID 31588227, 2019).
atherosclerosis (continued). "Our findings are in agreement with other studies reporting that Arg-1 could attenuate the function of iNOS, inhibit NF-κB activation and inflammatory cytokines in vitro, and decrease macrophage infiltration and inflammation in vivo in a rabbit model of atherosclerosis." (PMID 28168165, 2017). "Arginase 1 (ARG1), ATM, and CD80 are elevated with various forms of cardiovascular disease including the following: vascular dysfunction, coronary artery disease, and atherosclerosis in obese individuals." (PMID 36437471, 2022). "Mice lacking myeloid Arg1 or ODC1 have selective defects in continual efferocytosis and prevent atherosclerosis regression." (PMID 36710920, 2023).
parasite infection (23 papers, 2012 to 2025). "In contrast, alternatively activated M2 macrophages are susceptible to parasite infection, express arginase 1 (Arg1), and play a role in tissue repair." (PMID 37662946, 2023). "So far, we have shown that during experimental Chagas disease overexpression of IL-13 resulted in high Arg-1 expression and arginase activity that was associated with a decreased survival rate and enhanced parasitemia." (PMID 30555475, 2018). "Upregulation of MAPK14 proteins inhibit the expression of iNOS while upregulating the expression of Arginase-1 proteins which are associated with M2 polarization of macrophages during parasitic infection and bacterial sepsis." (PMID 29375545, 2017). "Numerous studies in allergic airway and parasitic diseases have reported that the classical caMph marker iNOS is increased and the typical aaMph marker Arg1 is decreased in macrophage cell-specific IL-4Rα deficient mice when compared to control groups." (PMID 25790379, 2015). "Increased susceptibility was associated with MKP-2−/− macrophages being inherently more susceptible than wild-type macrophages to parasite infection as a result of increased Arginase-1 expression and also reduced NO production." (PMID 23437409, 2013). "Despite these evolutional adaptations serving parasite survival, ARG1-expressing macrophages are in general designed to fight parasite infection by walling off toxic worm eggs through collagen deposition enabling their disposal." (PMID 39863828, 2025). "Myeloid ARG1 also regulates extracellular arginine availability and T cell responses in parasitic diseases and cancer." (PMID 39863828, 2025). "During parasite infection, activated T cells and eosinophils induce ARG1 expression in macrophages through production of IL-4 and IL-13 and activation of STAT6." (PMID 39863828, 2025). "During parasite infection, macrophages primarily display an anti-inflammatory M2-like phenotype, as characterized by the expression of specific effector molecules, such as arginase-1 (Arg1), Ym1 and resistin-like molecules (RELM)." (PMID 37564976, 2023). "M1 macrophages up-regulate NOS2 but down-regulate Arginase 1 (ARG1), limiting the parasite infection while the reverse is observed in M2 macrophages." (PMID 35925884, 2022). "Reportedly, supplementation with L-arginine increased the effectiveness of immune responses to parasitemia; L-arginine is a semi-essential amino acid necessary for cell proliferation and is the substrate of arginase 1 and iNOS." (PMID 35371021, 2022). "Infection of BALB/c mice with a lethal dose (2,000/mouse) of T. cruzi produced high levels of parasitemia and increased expression of iNOS and Arg-1 in heart tissue, consistent with our previous reports." (PMID 29337988, 2018). "This was mirrored in our study and endorsed our proposition that in parasitic diseases, an enhanced expression of arginase-1 is a feature of M2 polarized human monocytes/macrophages." (PMID 26496711, 2015). "In contrast, though ARG1 transcription was also induced during parasite infection, L-Arg pretreatment suppressed ARG1 expression." (PMID 26070945, 2015). "Arginase 1 is highly expressed in a “pro-regenerative” subset of macrophages, known as alternatively activated macrophages, in response to parasitic infection via the STAT6 pathway." (PMID 22629434, 2012). "Arginase 1 is also induced in classically activated (M1) macrophages in a STAT6 independent manner via the Toll–like receptor 2/MyD88 pathway following parasitic infection." (PMID 22629434, 2012). "Arg1 is essential in the anti-infection mechanism of several parasitic diseases." (PMID 37692380, 2023). "The existence of macrophages co-expressing Nos2 and Arg1 genes, exerting immunosuppressive phenotype, has also been described in other parasite infections such as Trypanosoma cruzi or Giardia lamblia, as well as during bacterial Mycobacterium tuberculosis infection." (PMID 36420267, 2022).
parasite infection (continued). "Moreover, neutrophils may promote ARG1 expression in macrophages upon parasite infection, leading to reduced helminth survival due to arginine depletion." (PMID 39863828, 2025). "An imbalance in Arg-1 activation over iNOS activity, with a resultant depletion of intracellular L-arginine, could be responsible for variations in infectious disease pathogenesis, as has been described for parasitic infections." (PMID 29077752, 2017). "In addition, neutralization of IL-4 in IL-27Rα-deficient mice or inhibition of Arginase-1 in Ebi3-deficient mice was essential to control the parasitemia, but did not alter the host survival." (PMID 29033934, 2017). "At day 23 after the last inoculation, when the inflammation began to appear, we observed that LmJ3OE parasite infection led to a significantly lower mRNA induction of IL1-0, IL-4 and ARG1, and an mRNA increase of IL12p35 compared to LmMC parasites’ infection." (PMID 33114674, 2020). "Although not statistically significant different, Arg-1 inhibition resulted in a decrease in parasitemia of IL-13tg to 3 × 105 trypomastigotes/ml." (PMID 30555475, 2018). "As NOS2, LRG-47 and ARG1 expression by macrophages was unaltered in vivo in IL-22−/− mice and IL-22 did not influence parasite killing by macrophages in vitro, the fact that the parasitemia was unaffected by the absence of IL-22 was not surprising." (PMID 27650379, 2016).
glioblastoma (22 papers, 2016 to 2025). The most malignant astrocytic tumor (WHO grade IV). "In relation to brain cancer, EVs from tumour-associated macrophages were shown to contain Arg1 and promote glioblastoma progression." (PMID 41488750, 2025). "We previously reported that Arg-1+ exosomes produced by in vitro reprogrammed tumor-associated macrophages (TAMs) promoted glioblastoma growth." (PMID 38001706, 2023). "One study demonstrated that mechanisms underlying the promotion of glioblastoma growth involved Arginase-1+ exosomes produced by the reprogrammed TAMs." (PMID 35600367, 2022). "Mechanisms underlying the promotion of glioblastoma growth involved Arginase-1+ exosomes produced by the reprogrammed TAMs." (PMID 32498400, 2020). "For example, in the glioblastoma microenvironment, IL-6 and CSF-1, which are produced by glioblastoma-associated endothelial cells, increase arginase-1 expression, which is mediated by HIF-2α activation in monocyte-derived macrophages." (PMID 32655574, 2020). "Increased ARG-1 expression is widely recognized as an indicator of anti-inflammatory activity in BMDMs of the glioblastoma microenvironment." (PMID 40191733, 2025). "In glioblastoma, IL-6 secreted by endothelial cells induces macrophage M2-like polarisation by increasing ARG1 expression." (PMID 37462801, 2023). "For example, using mouse glioblastoma as an experimental object, researchers used CSF-1R inhibitors to reduce the expression of Arg1 (arginase 1) and Mrc1 (CD206, mannose receptor) genes in the TME, thereby inhibiting tumor growth and metastasis." (PMID 34683963, 2021). "The IL-4 induced microglial phenotype shares some similarity with the glioblastoma (IL-4 secreting cells)-induced tumor-supportive microglial phenotype, including the increased expression of Arg1 gene." (PMID 34082793, 2021). "We also provide the first evidence for the role of arginase-1 in the glioblastoma progression mediated by TAM-derived exosomes." (PMID 32498400, 2020). "The data suggest that GBex-reprogrammed Arginase-1+ TAMs emerge as a major source of exosomes promoting tumor growth and as a potential therapeutic target in glioblastoma." (PMID 32498400, 2020). "Similar growth inhibitory effects were mediated by the arginase-1 inhibitor, confirming the key role of the arginase pathway in glioblastoma growth." (PMID 32498400, 2020). "An additional example of paracrine-acting MIF driving MDSC phenotypes came from the Lathia group which identified that glioblastoma (GBM) cancer stem cell (CSC)-secreted MIF increases MDSC immune suppressive activity in an arginase 1-dependent manner." (PMID 33324425, 2020). "Tumor histology showed recurrent glioblastoma, with less frequent interspersed TAMs and rare Arg1+ cells of predominant neutrophilic lineage." (PMID 27936099, 2016). "In UPN 100, a patient with newly-diagnosed glioblastoma, flow cytometry demonstrated that most Arg1 expression was in CD11b+/CD45+ or CD45- tumor-infiltrating leukocytes." (PMID 27936099, 2016). "In UPN 110 (recurrent glioblastoma), Arg1 was detectable in all tumor-infiltrating leukocytes by flow cytometry." (PMID 27936099, 2016). "Analysis of six additional newly-diagnosed glioblastoma tissue samples revealed that TAMs were more prevalent than neutrophils, but nearly all of these cells were Arg1-." (PMID 27936099, 2016). "A selective Arginase-1 inhibitor, nor-NOHA reversed growth-promoting effects of arginase-1 carried by TAM-derived exosomes, suggesting that GBex-reprogrammed Arginase-1+ TAMs emerge as a major source of exosomes promoting tumor growth and as a potential therapeutic target in glioblastoma." (PMID 35600367, 2022). "In intracranial U87 xenografts, immunostaining revealed that bevacizumab-resistant glioblastoma showed an increased amount of TAMs and increased M2/M1 ratio, defined by M2 markers (Arg-1, TGF-β, MMP9) and M1 markers (NOS2, CXCL10, IL-1β), compared to bevacizumab-sensitive glioblastoma." (PMID 34209679, 2021).